IL18 (interleukin 18)
Diseases named in the same sentence as IL18 in open-access papers (continued):
Sharing a sentence is not in itself a finding about the gene and the disease.
Cognitive impairment (46 papers, 2010 to 2025). Abnormal cognition is characterized by deficits in thinking, reasoning, or remembering. "A systematic review by Ribeiro-Santos, Teixeira and Vinicius found that MCP-1 and IL-18 levels were associated with cognitive impairments in schizophrenia." (PMID 35545617, 2022). "Furthermore, IL18 (Il18) deficiency in mice leads to mitochondrial dysfunction in hippocampal cells, resulting in depressive-like symptoms and cognitive impairment." (PMID 38139000, 2023). "Ultimately, mediation analysis suggested that IL-1β and IL-18 could explain 25.4 and 17.5% of effect of the risk of cognitive impairment related to 25(OH)D3 deficiency." (PMID 35370605, 2022). "The mediation analysis showed that IL-1β and IL-18 could explain 25.4 and 17.5% of effect of the risk of cognitive impairment related to 25(OH)D3 deficiency." (PMID 35370605, 2022). "Furthermore, mediation analysis has suggested that IL-1β and IL-18 partially mediate the relationship between vitamin D/25(OH)D3 deficiency and the risk of cognitive impairment in older people." (PMID 36293430, 2022). "For example, IL-18 is associated with disability and cognitive impairment in post-injury patients." (PMID 35978006, 2022). "In the present study, we report the results of the first formal examination, to our knowledge, of whether IL-10 and IL-18 promoter SNPs are associated with cognitive impairment in PD." (PMID 26830320, 2016). "IL-18 KO mice showed cognitive impairment and depressive-like behavioral changes, demonstrating the involvement of IL-18 in psychiatric and neurologic conditions." (PMID 39769266, 2024). "We reported that Il18−/− mice showed cognitive impairment and depressive-like behavioral changes compared with wild-type mice." (PMID 38139000, 2023). "This study aims to explore the potential of utilizing the RNFL thickness and serological concentrations of IL-18, irisin, CML, and RAGE as diagnostic indicators for Mild Cognitive Impairment (MCI) among individuals with T2DM." (PMID 38260156, 2023). "It is increased in the CSF of TBI patients, and levels of circulating IL-18 are correlated with chronic TBI patients’ cognitive impairment and disability severity." (PMID 37628746, 2023). "Scopolamine-treated mice have already been shown to have elevated levels of inflammatory cytokines (e.g., TNF-α, IL-1β, and IL-18) and cognitive impairment." (PMID 36294963, 2022). "The IL-18 levels show a peak during mild cognitive impairment compared to healthy controls and AD patients." (PMID 36293430, 2022). "Human IL-18 serum levels are elevated in patients with multiple sclerosis, Alzheimer’s disease, vascular dementia, and mild cognitive impairment." (PMID 26728085, 2016). "Specially, increased levels of serum IL-6 and IL-18 correlated with cognitive impairment in patients with cirrhosis of the liver and minimal hepatic encephalopathy." (PMID 26420028, 2015). "In patients with minimal HE, cognitive impairment correlates with serum levels of inflammatory cytokines IL-6 and IL-18." (PMID 26420028, 2015). "IL-18 is upregulated in AD brain and IL-18 production by peripheral blood cells is increased in AD patients, the level of which correlates with cognitive impairment." (PMID 23300647, 2012). "In the plasma, the levels of IL-18 were significantly elevated in patients with AD, vascular dementia, and mild cognitive impairment compared to the control group." (PMID 20113500, 2010). "In addition, increasing the abundance of the indole-producing gut microbiome in AD mice can reduce the release of inflammatory factors such as IL-18 and attenuate the inflammatory response, which improves cognitive deficits in AD mice." (PMID 39247699, 2024). "The NLRP3 inflammasome complex is considered a possible therapeutic target for preventing various cognitive impairments due to its response to microbial infections and environmental stimuli, and it can activate caspase-1 and promote the maturation of IL-1β and IL-18." (PMID 39203778, 2024).
Cognitive impairment (continued). "IL18 plays multiple roles in immune function, energy metabolism, and psychiatric disorders, and is also a therapeutic target for cancer immunotherapy, inhibition of body weight gain, and cognitive impairment." (PMID 38139000, 2023). "Our findings suggest that the IL-18 system, and perhaps inflammasome activation, could be an interesting path for future investigation of cognitive impairment in SMI." (PMID 36577840, 2023). "In first-episode psychosis patients, IL-18 levels are positively related to cognitive impairment." (PMID 36293430, 2022). "The analysis revealed that the risk of malnutrition increased with a higher number of comorbidities, female sex, cognitive impairment, and inflammation measured by a higher concentration of IL-8, logsTNFRII, and OPG; the risk of malnutrition was negatively associated with Il-18 level." (PMID 32297262, 2020). "Therefore, inflammasome NLRP3, ASC, caspase-1, GSDM-D, IL-1β, and IL-18 are key signaling molecules for inflammation and cell pyroptosis and are involved in the process of CI and other cognitive disorders." (PMID 31781266, 2019). "In addition, decreases in the expression levels of ASC, Caspase-1, and IL-1β/IL-18 have been shown to alleviate the cognitive impairment of gerbils after I/R, and ASC exacerbates ischemic neurological deficits and inflammatory reactions in an NLRP3-dependent manner." (PMID 38441564, 2024). "The levels of pyroptosis signaling pathway were significantly upregulated in cognitive impairment, together with the release of large amounts of inflammatory substances such as IL-1β and IL-18, resulting in a cascade of inflammatory reactions, which could be harmful to brain tissues." (PMID 37332874, 2023). "70% showed cognitive impairment (WMS-R score < 50) after MECT; this group showed significantly higher post-ECT levels of NLRP3, IL-18, and NF-κB compared to cognitively preserved participants (p < 0.05)." (PMID 40969698, 2025). "Future studies should examine the roles of IL-1β and IL-18, two inflammasome-related cytokines, in CKD-induced cognitive impairment." (PMID 34572437, 2021). "Notably, restoration of this pathway by administration of MCC950 or Ac-YVAD-CMK could reduce NLRP3-mediated overactivation of neuronal pyroptosis, downregulate the expression of mature IL-1β and IL-18, rescue neuronal damage, and reduce cognitive impairments in SAE mice." (PMID 30276509, 2019). "Fisetin attenuated histological injury, MDA levels, inflammasome pathway activation, and the mediated production of cytokines IL-1β and IL-18, apoptosis, as well as increased BDNF expression, and reduced astrocyte, microglial activation, and cognitive deficits following VaD." (PMID 35740470, 2022). "We found that isoflurane GA caused upregulations of hippocampal NLRP3, cleaved caspase-1, interleukin-1β (IL-1β), and IL-18 and the activation of pyroptosis, which is NLRP3 inflammasome-dependent; this consequently gave rise to neuronal damage and cognitive impairment in aged mice." (PMID 30524241, 2018). "To ascertain whether treatment with A. muciniphila prevented cognitive impairment by inhibiting hippocampal NLRP3‐mediated neuroinflammation activation, we assessed the expression levels of ASC, Cleaved Caspase 1, IL‐18, NF‐κB, p‐NF‐κB and NLRP3 in the hippocampus after the behavioral study." (PMID 40050112, 2025). "However, there has been a lack of research examining serum IL-18 changes in individuals with both T2DM and cognitive impairment, and how these changes correlate with cognitive function." (PMID 38260156, 2023).
influenza (45 papers, 2012 to 2025). An acute viral infection of the respiratory tract, occurring in isolated cases, in epidemics, or in pandemics; it is caused by serologically different strains of viruses (influenzaviruses) designated A, B, and C, has a 3-day incubation period, and usually lasts for 3 to 10 days. "For example, IL-18 has been shown to prevent further tissue damage and loss of tissue function when acting upon Treg cells during influenza infection." (PMID 39240187, 2024). "Increased mortality, massive cellular infiltration, and elevated NO production have been observed in Il18−/− mice infected with influenza A; with increased susceptibility to influenza reported for Nlrp3−/− and Casp1−/− mice." (PMID 35822051, 2021). "Given the importance of IL-18R/IL-18 signalling in potentiating NK cell activity, we examined IL-18Rα expression on NK and NK T cells throughout the course of mild and severe influenza disease." (PMID 41285788, 2025). "This IL-18-dependent activation suggests a protective role for MAIT cells in influenza and potentially in other inflammatory conditions involving IL-18 production." (PMID 38545100, 2024). "Intranasal vaccination with the IL-18 and IL-33 adjuvanted recombinant influenza vaccine significantly enhanced antigen-specific antibody responses in systemic compartments and mucosal sites and increased mouse survival during lethal influenza challenges." (PMID 33430259, 2021). "The modest (but statistically significant) increase in production of IFN-γ in response to low-dose IL-12 plus IL-18 observed 2 wk after influenza vaccination is highly reminiscent of the generation of memory-like NK cells in vitro with cytokine cocktails." (PMID 27233958, 2016). "In particular, the reduced levels of IL-1beta and IL-18 are in line with recent reports of impaired NLRP3 inflammasome function in elderly mice during influenza infection." (PMID 24642138, 2014). "Recent studies demonstrated that recombinant vaccines simultaneously expressing influenza antigens along with IL-18 significantly enhance the protective efficacy of influenza vaccines in chicken." (PMID 25431115, 2014). "Interestingly, IL-18–dependent MAIT cell activation was reported following influenza infection, suggesting a role for IL-18 in mediating MAIT cell activation during pregnancy, as it was found at increased concentrations in our analysis." (PMID 37036008, 2023). "IL-33 production is induced in influenza infected epithelial lung cells that in combination with IL-18, bind to their respective receptors (IL-18R and ST2) on regulatory T cells (Treg) and/or innate lymphoid cells (ILC) to promote lung tissue repair and inflammation control." (PMID 35479098, 2022). "As such, the gut microbiome was reported to influence DC migration to draining lymph nodes and T cell priming during influenza infection by providing signals leading to pro-IL1β and pro-IL18 expression at steady state and inflammasome activation upon influenza infection." (PMID 33905460, 2021). "Finally, influenza infection triggers NLRP3 activation, which lead to formation of large multimeric complexes called inflammasomes that cause release of IL-1/IL-18 and pyroptosis." (PMID 30337928, 2018). "Influenza infection-induced IL-12 and IL-18 might result in the activation of de novo ILC1s and/or transdifferentiation of ILC2s and/or ILC3s into IFN-γ-producing ILC1s." (PMID 29623077, 2018). "Indeed, they detected a strong accumulation of IL-18 in both subcapsular sinus and medullar macrophages on day 2 of influenza infection, suggesting that these resident macrophages are a source of IL-18." (PMID 29740428, 2018). "Most interesting, increased expression of pro-IL-18 with defective NLRP3 activation was observed in dendritic cells from elderly mice during influenza infection, highlighting that IL-18 upregulation may occur in the absence of NLRP3 activation." (PMID 28912710, 2017).
influenza (continued). "Combined stimulation with influenza and R848 resulted in markedly increased production of pro-IL-1β (153.9%, p = 2.22 × 10−16) and IL-1β (339.8%, p = 2.22 × 10−16), with more moderate but significant increases in caspase-1 (32.0%, p = 0.009) and IL-18 (8.5%, p = 2 × 10−5)." (PMID 35822051, 2021). "Interestingly, the magnitude of caspase-1 (p = 0.012) and IL-18 (p = 0.024) production in response to influenza + R848 was greater at Day 1 compared to baseline, while the opposite was true for IL-1β (p = 0.031) and pro-IL-1β (p = 0.024) secretion in response to influenza alone." (PMID 35822051, 2021). "To investigate this further, we tested whether influenza vaccination enhanced the response to higher concentrations of cytokines (in this case, 5 ng/ml IL-12 and 50 ng/ml IL-18) that were more in line with those used previously to cytokine-mediated human NK cell preactivation." (PMID 27233958, 2016). "To address this question, we stained lymph nodes on day 2 of influenza infection with antibodies against CD169, IL-1β, IL-18, and IL-33." (PMID 29249358, 2018). "It was reported that IL-12 and IL-18 can synergistically enhance IFN-γ production by NK cells, thereby enhancing their cytotoxic potential against influenza infection." (PMID 29623077, 2018). "Thus, influenza-induced secretion of IL-12 and IL-18 might further contribute to ILC1 activation." (PMID 29623077, 2018). "Following murine infection with influenza, aged DC show impairments in NLRP3 inflammasome/caspase-1 activation, and downstream IL-1β and IL-18 production, suggesting age-related impairments in DC pathogen sensing and/or innate activation." (PMID 22862959, 2012). "LAIV (like wild-type influenza) expresses M2 protein in infected cells and therefore activates NLRP3 inflammasomes, resulting in the production of the potent inflammatory cytokines IL-1β and IL-18." (PMID 39591131, 2024). "While IL-18 contributes to the antiviral response in influenza through the activation of lymphocytes, it does not appear to have a direct antiviral effect on rhinovirus." (PMID 39240187, 2024). "In an RCT of patients with influenza, combination therapy with oseltamivir and azithromycin showed significant improvement in the levels of inflammatory cytokines, such as IL-6, CXCL8/IL-8, IL-17, CXCL9/MIG, sTNFR-1, and IL-18." (PMID 37243228, 2023). "Upon influenza infection of the recipients, GFP+ ILC2s were found to have downregulated GATA3 expression and upregulated IL-12Rβ2 and IL-18Rα, becoming so-called ex-ILC2s that produced IFNγ upon ex vivo stimulation with IL-12 and IL-18." (PMID 36052086, 2022). "Several cytokines, including type I IFNs, IL-12, IL-15 and IL-18 are known to be important for NK cell activity against viral pathogens, but their roles during influenza infection specifically are not clear." (PMID 23300570, 2012).
kidney damage (45 papers, 2012 to 2025). "Further research is needed on the duration of the increase in IL-18 in various conditions of kidney damage, including those caused by kidney obstruction." (PMID 37363465, 2023). "The data obtained from this study indicate that IL-18 can be a more reliable biomarker in predicting kidney damage caused by renal obstruction than the NGAL biomarker." (PMID 37363465, 2023). "Neutrophil gelatinase-associated lipocalin (NGAL) and urinary interleukin 18 (IL-18) are markers of early kidney damage with different characteristics." (PMID 37363465, 2023). "AKI biomarkers such as kidney injury molecule 1 (KIM-1), neutrophil gelatinase-associated lipocalin (NGAL) and interleukin 18 (IL-18) are direct and far more specific indicators of kidney damage." (PMID 34571700, 2021). "In this study, IL-18 promoter polymorphism -137 is associated with the development of nephropathy in diabetic patients." (PMID 27703550, 2016). "A cross-sectional study conducted by Qasem and his colleagues evaluated the utility of two urinary biomarkers of kidney damage (Neutrophil Gelatinase-Associated Lipocalin and Interleukin-18)." (PMID 26361506, 2015). "Intraperitoneal administration of recombinant IL-18 has been shown to exacerbate nephropathy, whereas anti-IL-18 antibodies and IL-18 cDNA vaccines suppress IL-18 in vivo, thereby attenuating lymphocyte proliferation and nephritis." (PMID 41142814, 2025). "Increased TNF-α levels in cisplatin-induced kidney damage are accompanied by rises in IL-8, IL-1β, and IL-18, further promoting inflammation and damage." (PMID 39599345, 2024). "Novel kidney injury biomarkers (IL-6, IL-8, TNF-α, NGAL, KIM-1, MMP-9, and IL-18) were used in this investigation to assess kidney damage more accurately." (PMID 38420620, 2024). "Urinary interleukin 18 levels can be used as a predictor of kidney damage in acute-subacute PUJO cases but further studies are needed." (PMID 37363465, 2023). "Kidney damage was reduced with decreasing blood urea nitrogen, creatinine, interleukin-1β, and interleukin-18 levels." (PMID 36801911, 2023). "IL18 (interleukin-18) has a significant role as an inflammation mediator in the development and progression of nephropathy." (PMID 35843953, 2022). "As a pathogen-associated molecular pattern, uric acid can cause the activation of NLRP3 inflammasome and subsequent release of IL-1β and IL-18 and lead to severe kidney damage." (PMID 35309342, 2022). "IL-18 is created by proximal tubular cells during kidney damage and has shown potential in diagnosing ATI." (PMID 36091391, 2022). "The levels of IL-11 increase.Inhibition of IL-18 can significantly prevent kidney damage.CCL5 and IL-1α slightly increase.Inhibition of TNF-α cannot significantly reduce kidney damage.NLRP3 pathway is the key pathogenesis of inflammation." (PMID 34149721, 2021). "postoperative hour cystatin C, interleukin-18 (IL-18), and neutrophil gelatinase-associated lipocalin (NGAL) parameters were measured for early detection of kidney damage." (PMID 33118738, 2020). "Additionally, urinary IL-6, TWEAK and GDF15 correlated with kidney damage assessed by decreased eGFR, while urinary IL-17, IL-18, TWEAK and GDF15 correlated with kidney damage assessed as the magnitude of proteinuria." (PMID 39188767, 2024). "Urinary IL-18 levels can be used as a predictor of kidney damage in acute-subacute PUJO cases." (PMID 37363465, 2023). "Multiple promising biomarkers for kidney damage have been identified, with the most relevant and best-studied being neutrophil gelatinase-associated lipocalin (NGAL), CYC, kidney injury molecule-1 (KIM-1), β2M, and interleukin-18 (IL-18)." (PMID 37623466, 2023). "Urine IL-18 levels can be used as a predictor of kidney damage in early PUJO cases (acute stage)." (PMID 37363465, 2023). "Markers of kidney damage: kidney injury molecule (KIM)-1, interleukin (IL)-18, and neutrophil gelatinase-associated lipocalin (NGAL) may ease early diagnosis of AKI." (PMID 37958774, 2023).